IL17A (interleukin 17A)
Diseases named in the same sentence as IL17A in open-access papers (continued):
Sharing a sentence is not in itself a finding about the gene and the disease.
infection (continued). "Whereas the modest expression of IL-17A in the context of a low-dose infection with Mtb H37Rv does not impair mycobacterial burdens, the proinflammatory cytokine appears to contribute to protection against Mtb under conditions of IL-17A overproduction." (PMID 33375150, 2020). "IL-17A showed no significant variation between infection subtype profiles in mRNA expression." (PMID 33316950, 2020). "Moreover, the IL-17A and IFN-γ production was markedly increased after the infection." (PMID 33193292, 2020). "Indeed, IL-17A, which was hardly detectable in H37Rv infected mice (data not shown) was readily induced by HN878, but IL-17A expression was significantly lower in males compared to females early during infection." (PMID 32198367, 2020). "Deficient adaptive immunity in the periphery is likely influencing the NP response to infection, as several inflammatory cytokines and chemokines were higher at onset and/or sustained longer in sOP children during AOM pathogenesis, including CCL2, IL-12, IL-17A, and TNF-a." (PMID 32595639, 2020). "Furthermore, we observed that the frequency of Vγ4+ γδ T cell that express IL‐17A did not change after infection with a higher dose of influenza virus." (PMID 31777067, 2020). "We hypothesized that Treg cells contribute to this initial IL-17A response through transient expression of IL-17A and that persistent mucosal colonization with P. gingivalis drives Th17 cells toward an IFN-γ phenotype at later stages of infection." (PMID 32391008, 2020). "It was concluded that γδ T cells were a viable source of IL-17A in the absence of neutrophils and may be a significant source of leukocyte recruitment early on during infection with C. neoformans." (PMID 33042164, 2020). "We do not know precisely which cells produce IL-17A/F and IL-22 in the MG during infection." (PMID 33059767, 2020). "In addition to increased IL-10, patients with gram-positive infections had higher levels of IL-17A and a neutrophil predominance in the CSF when compared to patients with gram-negative shunt infection." (PMID 30626412, 2019). "The outcome of this study shows that a G. muris infection in pre-weaned mice failed to trigger an IL-17A response, which could explain the prolonged course of infection in comparison to older mice." (PMID 31222079, 2019). "While shunt infections are biofilm rather than planktonic infections like brain abscess, the increased levels of IL-17A and neutrophil predominance in the CSF in our cohort suggest a Th17 response to gram-positive shunt infections in humans may predominate." (PMID 30626412, 2019). "The outcome of the study showed that a G. muris infection in pre-weaned mice failed to trigger a protective IL-17A response, which could explain the prolonged course of infection in comparison to older mice." (PMID 31222079, 2019). "Concurrently, IL-17A+ Th17 cells were not significantly increased during infection." (PMID 31703440, 2019). "Strikingly, a significant increase in IFNγ gene expression was measured in gastric tissue from mice vaccinated with WC H. pylori antigen and α-GalCer compared with the infection control group, whereas no significant increase in IL-17A gene expression was observed 3 weeks post infection." (PMID 31666991, 2019). "However, the ambiguous group (cPCR(-) qPCR(+)) showed a significant decrease of IL-17A after 6 months indicating no persistent infection." (PMID 31553732, 2019). "Comparing the two mouse lines at steady state and two weeks (or 7 days, data not shown) post infection, we detected no increase in intestinal IL-17A transcript levels and found stable frequencies of IL-17A producing Th17 cells and ILC3 in the small intestine and PP." (PMID 31889073, 2019). "Similarly, IL-17A overexpression led to increased survival of animals and decreased bacterial burden in Gram-negative pathogen infection models." (PMID 31614857, 2019).
infection (continued). "These seemingly contradictory results have arisen not least because of indirect assessments of IL-17A production during infection by either measuring Il17a and Il17f transcripts in crude tongue extracts or monitoring IL-17A promoter activity in Il17aeYFP fate reporter mice." (PMID 29782555, 2018). "Besides, it has also been shown that absence of IL-17A did not alter survival after 8 weeks of infection." (PMID 30409128, 2018). "However, we were able to compare the relative proportion of each cell type before and after infection that could produce IL-17 after ex vivo stimulation with PMA and ionomycin and staining for intracellular Il-17A." (PMID 29813133, 2018). "In addition, levels of il17a and il22, transcripts that code for TH17 cytokines were higher in lungs from stat3fl/fllysm cre mice than in those from littermate controls when measured at 4 and 8 weeks after infection." (PMID 29338039, 2018). "However, CE-induced IL-17A (protein) was not a reliable indicator of M. bovis infection in cattle that were confirmed positive for infection by nested PCR." (PMID 29560355, 2018). "Since the lack of IL-17A leads to enlarged worms concomitant with reduced Foxp3+ Treg at the site of infection, we further analysed Th17 cell populations in the TC and mLN on day 28 p.i. using flow cytometry according to the applied gating strategy (Online Resource 5)." (PMID 29931394, 2018). "Collectively, H9N2 AIV infection enhanced the expression of proinflammatory cytokines, such as IFN-α, IL-17A, IFN-γ, and IL-22, and promoted the proliferation and translocation of Proteobacteria, especially E. coli, which might be induced by the injury of mucous layers and tight junctions." (PMID 29783653, 2018). "However, CE-induced IL-17A (protein) was not a reliable indicator of M. bovis infection in cattle that were confirmed positive for infection by nested PCR, and levels of IL-17A (mRNA and protein) were lower than those of IFN-γ." (PMID 29560355, 2018). "The reason for this phenomenon is not known, but recent studies have shown that IL-17A (mRNA and protein) may be predictive of both vaccine efficacy and lesion severity when measured after vaccination and during infection, respectively." (PMID 29560355, 2018). "Expression of an array of cytokines (CSF3 [G-CSF], IFNγ, IL-1β, IL-6, IL-22, IL-17A, and IL-10), chemokines (CCL20, CXCL2 and CXCL9) and receptors (CD40) known to be involved in the regulation of S. pneumoniae inflammatory response was measured at 0, 6, 24, and 48 h post-infection." (PMID 30333823, 2018). "Interestingly, patients with chronic mucocutaneous candidiasis were shown to exhibit defects in IL-17F and IL-17RA but not IL-17A, indicating that IL-17F has a defined protective role against this infection." (PMID 29048384, 2017). "Interestingly, the infection induced a recall response in the IL-17A WBA (but not in the IFN-γ WBA) in both groups, 7 days only after the challenge." (PMID 28611405, 2017). "CD1dhighCD19+ B cells were identified as the dominant IL-17A secreting subset, accounting for approximately 80% of the population, while CD1dlowCD19+ B cells were responsible for the production of only 20%, regardless of the presence or absence of infection." (PMID 28732522, 2017). "Interestingly, we found that IL-17A expression increased in SS1/SS1 and SS1/AM1 infection, while no significant changes in IL-17A expression were observed in AM/AM1 infected group as compared to control." (PMID 28286572, 2017). "In contrast, all CD4+IFNγ-/- T cell recipients whether treated with isotype antibody or anti-IL-17A were negative for R. typhi in the organs when the experiment was terminated on day 26 post infection." (PMID 28222146, 2017). "The expression of Foxp3 and IL17a was not changed 7 days after infection in both groups." (PMID 29033934, 2017).
infection (continued). "Whilst T helper cells could obviously not be measured in antibody treated mice, an absence of induction of Il4, Il13 and Il17a mRNAs in the lung following infection supported an absence of Th2 and Th17 responses in CD4+ cell depleted mice." (PMID 27683080, 2016). "IL-17A and IL-17F act on many non-immune cells, including epithelial cells, inducing: (i) production of chemokines that in turn mobilize and recruit neutrophils and macrophages to the site of infection; and (ii) production of anti-microbial peptides." (PMID 26812180, 2016). "Compared to IL17A, IL17F was found to be a more potent inducer of CXCL5, a known neutrophil recruiter, indicating that F. hepatica may avoid excessive neutrophil recruitment during infection by suppressing the IL17F/CXCL5 axis." (PMID 27661612, 2016). "Thus, in a model of infection and chemotherapy adequate to observe reactivation of M. tuberculosis infection in the complete absence of TNFα, there was no major effect of IL-17A neutralization." (PMID 27853279, 2016). "In contrast, M28 GAS elicited significant cytokine increases in TNF-α, IL-17A, IL-6, IL-1β, and IL-22, as early as 3 to 7 days post-infection in the estradiol pulse model, and a significant cellular infiltrate in the lumen was observed in colonized WT mice compared to non-infected or IL-17A−/− mice." (PMID 27241677, 2016). "We next investigated whether the absence of IL‐17A affected the antigen‐specific Th1 immune‐response to mycobacterial antigen after i.t. infection with M. tuberculosis at chronic stage." (PMID 27980775, 2016). "At this late stage of infection it was up-regulated in activated CD4+ T cells of both wt (mean = 67.9-fold) and Tnf-/- (mean = 48.6-fold) mice to a similar extent, although expression of IL-17A was generally low and barely detectable either by real-time PCR or by intracellular cytokine staining." (PMID 26834705, 2015). "Indeed, IL-17A and IL-17F expression in the infected tissue is induced rapidly after infection, suggesting that the relevant source of IL-17 for fungal control is produced by innate and not by adaptive cells." (PMID 26274976, 2015). "Therefore, one can deduce that at least in vaccinated mice infected with influenza virus, IL-17A secretion by either Th17 cells and/or additional sources does not play a role in viral control during the first 5 days of infection." (PMID 24465206, 2014). "However, blockage of the heterodimer IL-17A/F by antibody treatment did not reduce inflammation 24 h and 48 h after infection." (PMID 24699535, 2014). "While UV-RSV induced similar levels of IL-8 mRNA as infection by (live) RSV in the absence of IL-17A, we observed no synergistic enhancement of IL-8 mRNA expression and a modest, albeit highly significant, enhancement of protein expression when IL-17A was added." (PMID 24194936, 2013). "Further, upregulation of IL-17A production by PGI2 might protect against extracellular pathogens, such as Klebsiella pneumoniae or Mycoplasma pulmonis that require IL-17A to resolve the infection." (PMID 22590492, 2012). "Thus, the significant increase in IL-17A production observed in the lungs of mice during infection with the transgenic C. neoformans strain H99γ appears not to be associated with a general induction of Th17-type cytokines." (PMID 21359196, 2011). "Also, depletion of IL-17A during infection with C. neoformans strain H99γ resulted in no changes in any other pulmonary cytokine tested." (PMID 21359196, 2011). "The expression of IL-17A was mostly below detection threshold in the non-lymphocyte cells (determined as all of the cells that were not included in the Lymphocyte Gate) throughout the course of infection." (PMID 20585449, 2010). "As opposed to IFNγ and IL-6, the production of IL-17A could not be further induced by infection doses beyond 10×LD50." (PMID 20585449, 2010). "CD8+ T cells failed to produce IL-17A even at the high infection dose (B1)." (PMID 20585449, 2010).
infection (continued). "Exogenous airway administration of IL-17A or of IL-23 had a limited yet consistent effect of delaying the onset of death from a lethal dose of LVS, implying that IL-17A may be involved in restraining the infection." (PMID 20585449, 2010). "Interestingly, NK T-cells in the murine lung are not strong producers of IL-17A or IFN-γ during C. deneoformans (B3501) infection, suggesting there may be strain or species differences that influence NK T-cell function." (PMID 39452664, 2024). "ETBF infection-induced inflammation could also promote colonic tumorigenesis in APCMin+/− mice, which is dependent on the interleukin (IL) 17 response, as indicated by data showing down-regulation of ETBF-mediated tumorigenesis when IL-17A is neutralized by antibody or genetic abrogation in vivo." (PMID 38203534, 2023). "Hence, robust production of IL-17A in mice infected with the hypervirulent isolate Mycobacterium tuberculosis (Mtb) HN878 mediates protection, while the cytokine is dispensable for protective immune responses against low-dose infection with the less virulent strain H37rv." (PMID 36139450, 2022). "However, neither neutralization of IL-17A nor internalization of the γδTCR affected the early control of Lm dissemination and replication in 2-3- and 19-20-month-old or older mice during primary infection." (PMID 35501808, 2022). "However, IL-17A treatment prior to infection did not lead to increased viral burden in SGs 14 dpi." (PMID 31239384, 2019). "Thus, to further decipher the role of IL-17A in early phase of infection, we determined whether the lack of IL-17A during infection with Litomosoides sigmodontis altered parasite burden or immune responses like IFN-γ secretion in mice." (PMID 29931394, 2018). "However, in a less virulent strain infection, the host may control bacterial growth in a fashion independent of IL17A." (PMID 29743811, 2018). "However, infected Ccr2-/- mice, in which CD11b+Ly6Chigh monocytes recruitment to the infected tongue was strongly impaired, displayed no defect in IL-17A production on day 1 post-infection by any of the three CD90+ cell subsets (TCRβ+, TCRγδ+, ILCs) compared to WT control mice." (PMID 29782555, 2018). "However, the production of IL-17A during infection has not always been correlated with protection." (PMID 27334720, 2016). "Interestingly, a significant induction (8 to 28 fold) of IL-22, IL-17A and IL-17F was also observed for the avirulent strain, while induction of the eight next most expressed cytokines during infection with the virulent strain were either not induced or induced weakly (<2-fold)." (PMID 22675469, 2012). "In the present study, we found that the inhibition rate of Cm growth was not increased by increasing the concentration of IL-17A when the cells were treated with 200 ng/ml IFN-γ, suggesting that excessive production of IL-17A may not be helpful for controlling Cm infection." (PMID 22745717, 2012). "Our results showed that bacteria-specific CD4+ T cells producing IL-17A, but not those producing IFN-γ, were decreased in coinfection compared with bacterial single infection." (PMID 37222516, 2023). "After experimental infection with BCG, the absence of IL-17A results in a significant decrease in neutrophil recruitment to the infected lung, while mycobacterial containment is not affected." (PMID 36139450, 2022). "One study provided evidence that liver fluke infections can induce significantly higher IL-17A and IL-22 expression levels than healthy controls and CCA patients without an infection." (PMID 33851257, 2021). "Conversely, IL-17A, TNF-α, and IFN-γ secretion were strongly induced in the colon of CR-infected mice compared to non-infected mice at day 10 of infection." (PMID 33654214, 2021). "Concomitantly, IL-33 inhibits the differentiation of IL-17A-producing CD4+ T cells, which have the potential to reverse the negative effect of IL-33 during infection." (PMID 33654214, 2021).
infection (continued). "At the same time point post-infection, we also found that expression of the activation marker CD69 was upregulated on CD4+ T cells in the lungs of WT but not Il17a-KO mice." (PMID 32636457, 2020). "On the other hand, Nc-Spain7 infection did not upregulate TGF-β1, IL-6 and IL-17A expression in bovine placentas at any time assayed." (PMID 32552750, 2020). "Infection resulted in an increase in antigen-specific cell proliferation, IFN-γ and IL-10 production by PBMC, but not IL-4 or IL-17A." (PMID 32487248, 2020). "Infection of (reporter-less) Rag1-/- mice revealed, as expected, an overall reduction of total CD90+ and CD90+IL-17A+ cells due to the absence of TCRβ+ and TCRγδ+ cells." (PMID 29782555, 2018). "Protection is dependent on MR1, IFN-γ and GM-CSF, but not IL-17A, TNF or perforin, and enhanced protection is detected earlier after infection of mice antigen-primed to boost MAIT cell numbers before infection." (PMID 30135490, 2018). "In TBLN and tonsils, CD4+ T cells of only a few infected animals responded with IL-17A production to APP-CCE stimulation, regardless of the time post infection." (PMID 28166835, 2017). "Infection of both healthy and type 2 DM PBMCs with SGH04 or NUH29 failed to produce detectable levels of IL-17A and TNFRI after 24-h post-infection (not shown)." (PMID 28936426, 2017). "Whereas IFN-γ, IL-1β, IL-10, IL-12/IL-23p40, IL-17A, KC and MIG were not produced after infection or LPS-stimulation, elevated MCP-1 levels were measured only at 72–96 h (data not shown)." (PMID 28697801, 2017). "It was observed that rTgHSP70 immunization did not alter the production of IL-2, IL-4, IL-6, IL-10, IL-17a, IFN-γ, nor TNF, although infection with T. gondii promotes the production of inflammatory cytokines IL-6, IFN-γ, and TNF in all groups of mice." (PMID 28487847, 2017). "We found that macrophages from gp91phox−/− and WT mice produced similar levels of IL-6, TNF-α, IL-17A and CXCL-1, MCP-1 and IL-10, regardless of infection with L. amazonensis." (PMID 27056545, 2016). "In contrast, IL-17A was produced after HCV antigen stimulation in both those that controlled and those that did not control infection, at presentation and subsequent time points." (PMID 27124305, 2016). "In the present study, however, neutrophil accumulation and TNF-α, IL-1β, IL-17A and MIP-2 synthesis in the lungs after infection with S. pneumoniae were not significantly different between WT and Dectin-2KO mice." (PMID 26727976, 2016). "Interestingly, IL-20 has been previously shown to play a rather negative role in host defense; infection with Staphylococcus aureus led to the early up regulation of IL-20 family members (IL-19, IL-20 and IL-24), inhibiting the local generation of IL-1β and IL-17A." (PMID 26023727, 2015). "When anti-IL-17A Ab was injected i.p. into mice daily for 6 days, beginning from 24 h post-RRV infection, compared with RRV-primed mice without anti-IL-17A Ab injection, the survival rate was increased and weight gain was improved." (PMID 26325187, 2015). "During infections with T. borreli, we observed an up-regulation IFN-γ2, but not of IL-17A/F2, in head kidney and spleen." (PMID 20885956, 2010). "Since we demonstrate that the presence of IL-17A is important for protection from LVS, but the IL-17A-secreting γδ T cells are non-essential, it could be speculated that other cellular sources of IL-17A, such as Th17 -cells, produce sufficient amounts of IL-17A to resolve the low-dose infection." (PMID 20585449, 2010). "Indeed, 8d post-infection, it was primarily TCD8+, not TCD4+, that produced IL-17A upon the restimulation of αβ T cells from infected skin." (PMID 38543790, 2024). "Regardless of CLR treatment, CFA+GLA-SE/CDG immunization significantly elicited Mav CFA-specific CD4+CD44+CD62 L− T cells producing IFN-γ+IL-17A+, and IFN-γ+TNF-α+ but not IFN-γ+IL-2+ in the lungs in the CFA+GLA-SE/CDG-immunized group compared with those in the infection control group." (PMID 35499090, 2022).